ATF4 (activating transcription factor 4)
Diseases named in the same sentence as ATF4 in open-access papers (continued):
Sharing a sentence is not in itself a finding about the gene and the disease.
lymphoma (11 papers, 2017 to 2025). A malignant (clonal) proliferation of B- lymphocytes or T- lymphocytes which involves the lymph nodes, bone marrow and/or extranodal sites. "Hence, ATF4 is aberrantly expressed in primary murine and human lymphomas, where it appears to be linked to SIRT3 expression and inversely correlated with autophagy." (PMID 35019856, 2022). "We discovered the link between SIRT3 and ATF4 in DLBCL cells, which connected lymphoma amino acid metabolism with ATF4 translation via metabolic stress signals." (PMID 35019856, 2022). "Using Western blots, we showed that indeed ATF4 protein levels were significantly decreased in VavP-Bcl2;Sirt3−/− versus VavPBcl2;Sirt3WT primary lymphomas." (PMID 35019856, 2022). "Western blots performed in primary human DLBCLs and GC B cells revealed generally high levels of ATF4 in the lymphomas versus their normal B-cell counterparts." (PMID 35019856, 2022). "For example, studies in murine Eμ-MYC pro–B-cell leukemia/lymphomas suggested that ATF4 is induced by ER stress and MYC-induced nutrient exhaustion." (PMID 35019856, 2022). "Furthermore, ATF4 ablation significantly reduces in vitro clonogenic survival of MEFs with high c‐Myc level and extends tumor‐free and overall survival in syngeneic mouse model of lymphoma with hyperactive c‐Myc." (PMID 32310340, 2020). "To validate the reporter in our lymphoma system, we performed Western blots in DLBCL cells expressing the ATF4-5′UTR-GFP after induction of SIRT3 or control shRNA." (PMID 35019856, 2022). "We first demonstrated that SBP enzymes are overexpressed in BL, compared to another aggressive lymphoma, DLBCL, and transcriptionally controlled by MYC via ATF4." (PMID 32138178, 2020). "In lymphoma cells, both c‐Myc and N‐Myc activate PERK‐eIF2α‐ATF4 signaling, which induces cytoprotective autophagy and attenuates ER Ca2+ release to support malignant transformation and survival." (PMID 32310340, 2020). "Given our data showing that SIRT3 is required to maintain ATF4 expression in DLBCL cell lines, we next examined whether this was also the case in primary lymphomas developing in vivo." (PMID 35019856, 2022). "Given that ATF4 shRNA also impaired lymphoma cell growth, we wondered whether further antilymphoma activity would be gained by also targeting DLBCL cells through inhibition of ATF4 translation." (PMID 35019856, 2022). "In BM-resident lymphoma cells, CTX induced ER stress that resulted in the ATF4-mediated pathway." (PMID 34164401, 2021). "Finally, although ATF4 protein showed positive correlation with the relative abundance of phospho-EIF2A (p-EIF2A/EIF2A), the phospho-EIF2A levels only showed the trend of decrease in Sirt3−/− versus Sirt3WT lymphomas cells but was not statistically significant." (PMID 35019856, 2022).
osteoporosis (11 papers, 2009 to 2025). A condition of reduced bone mass, with decreased cortical thickness and a decrease in the number and size of the trabeculae of cancellous bone (but normal chemical composition), resulting in increased fracture incidence. "Collectively, our findings revealed a novel mechanism of osteoporosis caused by simulated microgravity, regulated by Piezo1/β‐catenin/ATF4 in BMSCs, which may be a potential therapeutic target for osteoporosis, especially caused by weightlessness or disuse." (PMID 37759400, 2023). "The mitogen-activated protein kinase (MAPK) pathway has been reported to be closely related to osteoporosis, and ATF4 is involved in the regulation of osteoblast differentiation by the MAPK signaling pathway." (PMID 38542323, 2024). "Since SATB2, ATF4 and Runx3 are three key mediators of osteoporosis, western blot analysis was used to detect the expression levels of their proteins." (PMID 34043680, 2021). "Collectively, these studies demonstrated that, SATB3, Runx3 and ATF4 participated in the progression of osteoporosis." (PMID 34043680, 2021). "Collectively, Runx1 maintains adult bone homeostasis from bone loss though up-regulating Bmp7/Alk3/Smad1/5/8/Runx2/ATF4 and WNT/β-Catenin signaling pathways, and targeting Runx1 potentially leads to novel therapeutics for osteoporosis." (PMID 33476325, 2021). "Several abnormalities, including osteoporosis, microphthalmia and abnormal hematopoiesis, found in ATF4 knockout (KO) mice reflect the significant role of ATF4 in mammalian development." (PMID 30705506, 2019). "Genetic interaction between ATF4 and Hop2 was best demonstrated by osteopenia (low bone mass) in the Atf4+/−:Hop2+/− double heterozygous (het) mice, which is identical to a low bone mass in Hop2−/− mice and milder than osteoporosis in Atf4−/− mice." (PMID 34600885, 2021). "Furthermore, ATF4 (activating transcription factor 4) has been identified as an osteogenic factor as it can modulate osteoporosis development." (PMID 34043680, 2021). "Similarly, indiscriminate inhibition of miR-214 to treat osteoporosis might inadvertently unleash ATF4-mediated calcification in the valve." (PMID 41584300, 2025). "Therefore, ATF4 may provide a potential new therapeutic target for improving bone mass and for treating metabolic bone diseases such as osteoporosis." (PMID 19851510, 2009). "We further studied the relationship between activating transcription factor 4 (ATF4) and the extracellular signal-regulated kinase (ERK) signaling pathway and osteoporosis by using mouse embryonic osteoblastic precursor cells (MC3T3-E1)." (PMID 38542323, 2024). "Runx1 maintained adult bone homeostasis and bone differentiation though upregulating Bmp7/Alk3/Smad1/5/8/Runx2/ATF4 and WNT/β-Catenin signaling pathways, suggesting that targeting Runx1 might be a novel therapeutics for osteoporosis." (PMID 37156809, 2023). "PPIs could disturb Ca2+ homeostasis in the ER, increase [Ca2+]I, and activate the Calpain-2/Caspase-12 and Grp78/ATF4/CHOP pathways, ultimately triggering osteoporosis." (PMID 35183103, 2022).
retinal degeneration (11 papers, 2014 to 2025). Degeneration of the retina. "Consistently, 4EHP affected ATF4-associated pathological phenotypes, including parkin mutants’ lethality and light-dependent retinal degeneration." (PMID 41436469, 2025). "In another model associated with ATF4 signaling, we examined light-dependent retinal degeneration, a phenotype accelerated by the loss of PERK or crc51." (PMID 41436469, 2025). "Conversely, ATF4-deficiency in ADRP retinas results in a significant delay in the onset of retinal degeneration and increases photoreceptor survival." (PMID 27144303, 2016). "The functional test demonstrated that ATF4 deficiency in T17M significantly preserves vision in mice with retinal degeneration." (PMID 27144303, 2016). "This could explain why T17M rhodopsin mice with inherited retinal degeneration experience a preservation of retinal function and photoreceptor cell death when their retina is deficient in TNFa, a downstream ATF4 target." (PMID 29326555, 2017). "Using C57Bl/6 mice, it was shown that ATF4 single-knockdown (ATF4+/−) of T17M was sufficient to yield a therapeutic response by significantly delaying retinal degeneration, whereas double-knockdowns enhanced the observed effect." (PMID 36840007, 2023). "We revealed that a 2.3-fold increase in ATF4 triggers retinal degeneration in wild type mice and mimics conditions with ATF4 over-expression in transgenic T17M rhodopsin retinas." (PMID 29326555, 2017). "Conversely, ATF4 knockdown retarded retinal degeneration in 1-month-old T17M Rhodopsin mice and promoted photoreceptor survival, as measured by scotopic and photopic ERGs and photoreceptor nuclei row counts." (PMID 27144303, 2016). "Our data indicate that augmented ATF4 signals during retinal degeneration plays a cytotoxic role by triggering photoreceptor cell death." (PMID 27144303, 2016). "Based on our results in ATF4 knockout mice and adeno-associated viral (AAV) delivery of ATF4 to the retina, we validated a novel therapeutic approach targeting ATF4 over the course of retinal degeneration." (PMID 27144303, 2016). "Taken together, these findings support the notion that preferential activation of apoptosis vs. autophagy in T17M retinas, and alternatively, autophagy vs. apoptosis in T17M ATF4+/- mice are important event in retinal degeneration." (PMID 27144303, 2016). "We showed, in a separate experiment, that ATF4 over-expression was cytotoxic for photoreceptors and induced severe retinal degeneration." (PMID 27144303, 2016). "Overall this indicates that PERK signaling in general and ATF4 in particular, is a target for delaying retinal degeneration in ADRP patients." (PMID 27144303, 2016). "We can however propose that increased ATF4 expression during retina degeneration contributes to T17M photoreceptor cell death." (PMID 27144303, 2016). "We have demonstrated that mice expressing mutant and truncated rhodopsins show dramatically elevated ATF4 levels, while other investigators have detected ATF4 upregulation in different models of inherited retinal degeneration." (PMID 29326555, 2017). "The major contribution of ATF4 knockdown to the mechanism of retinal degeneration is likely through a reduction of overall ER stress response, induction of an antioxidant program, and restoring of autophagy, which together result in a delay of apoptotic photoreceptor cell death." (PMID 27144303, 2016). "However, by P90, the T17M ATF4+/- retinas showed a 37% loss of photoreceptor cells when compared to C57BL6, suggesting delayed retinal degeneration." (PMID 27144303, 2016). "Our data also validate ATF4 as a potential therapeutic target for retarding retinal degeneration." (PMID 27144303, 2016). "Thus, our data revealed that sustained ATF4 overexpression in photoreceptors provokes severe retinal degeneration in both wild-type and degenerating retinas through activation of apoptosis." (PMID 27144303, 2016).
retinal degeneration (continued). "Diminishing ATF4-dependent cellular stress leading to reduction of apoptosis and enhancement of autophagy may delay the onset of retinal degeneration." (PMID 27144303, 2016). "Similarly, ATF4 knockdown also markedly delayed retinal degeneration in 3-month-old ADRP animals." (PMID 27144303, 2016). "More research is required to fully understand the dynamics of ATF4 and CHOP signaling in glaucomatous retinas and ER stress’s role in glaucomatous retinal degeneration." (PMID 40076484, 2025). "We have demonstrated for the first time that ATF4 overexpression accelerates retinal degeneration whereas genetic ablation of ATF4 mitigates retinal degeneration and significantly protects ADRP photoreceptors from rapid deterioration in ATF4+/- mice." (PMID 27144303, 2016). "Elevation of ATF4, a mediator of PERK UPR signaling, accompanies progressive retinal degeneration." (PMID 27144303, 2016). "However, the role of ATF4 signaling in age-related retinal degeneration of ninaEG69D mutant adults has not been established." (PMID 32938929, 2020).
Hypertension (10 papers, 2015 to 2026). The presence of chronic increased pressure in the systemic arterial system. "Their transcription levels correlate with the transcription levels of several genes encoding transcription factors associated with the response to oxidative stress, including transcription factors associated with hypertension (Arnt, Atf4, Ddit3, Foxo1)." (PMID 39594444, 2024). "We conclude that ATF4 plays an important role in regulating gut microbiota and VK2 production, providing new insights into the association between ATF4 and development of salt-induced hypertension in mice, meanwhile contributing to the development for a new preventive strategy of hypertension." (PMID 33282868, 2020). "Therefore, we use a novel approach to investigate the association between ATF4 and hypertension and the mechanism of action of ATF4." (PMID 33282868, 2020). "Second, while the role of ATF4 in hypertension has been demonstrated in previous studies, its specific effects on calcium overload and ferroptosis warrant further investigation." (PMID 41019540, 2025). "We further investigated THSWD’s molecular mechanisms on hypertension, focusing on its impact on ATF4-related calcium overload and ferroptosis." (PMID 41019540, 2025). "This study demonstrated that THSWD significantly ameliorated high salt-induced hypertension and vascular damage by alleviating calcium overload and ferroptosis through ATF4 regulation." (PMID 41019540, 2025). "Increasing Ang II due to hypertension is known to enhance the expression of ER stress-related genes such as Chop, Atf4, Bip, and Gadd45." (PMID 35111238, 2022). "The PCA plot revealed significant differences in gut microbial community structure of ATF4 participation in the development of hypertension induced by high salt in mice (R2 = 0.3264, p = 0.001)." (PMID 33282868, 2020). "To exhibit the mechanisms of action of ATF4 in the development of hypertension induced by high salt in mice, we analyzed composition of the gut microbiota and serum levels of the microbial metabolite VK2 in high-salt-induced hypersensitive mice." (PMID 33282868, 2020). "However, the role of THSWD in regulating ferroptosis in hypertension, particularly through the ATF4 pathway, remains largely unexplored." (PMID 41019540, 2025). "Through miRWalk software prediction, we discovered that miR-1283 might regulate differentially expressed genes related to hypertension, and confirmed that ATF4 is a target gene of miR-1283." (PMID 41019540, 2025). "Besides, ATF4 was found to enhance endothelial inflammatory response by targeting hypertension-related miR-1283." (PMID 33898454, 2021). "Therefore, our study shows that gut microbiota and VK2 play a role in the participation of ATF4 in hypertension, and these interactions are the possible potential mechanism of ATF4 participating in high-salt diet-induced hypertension." (PMID 33282868, 2020). "Therefore, it is of great importance to study the mechanisms of ATF4 involvement in the development of hypertension from the perspective of gut microbiota." (PMID 33282868, 2020). "It is also noteworthy that ATF4 may affect the intestinal microenvironment closely related to hypertension through directly regulating the production of gut microbial metabolites, thereby providing the theoretical basis for its involvement in hypertension." (PMID 33898454, 2021). "However, the specific mechanism of action of ATF4 in the development of hypertension remains unclear." (PMID 33282868, 2020). "Therefore, we sought to use Atf4± and WT mice to determine whether ATF4 regulates the blood pressure and endothelial function in high-salt diet-induced mice and to investigate the microbiota-related mechanism of action of ATF4 in hypertension." (PMID 33282868, 2020). "These chemical chaperones have been found to inhibit the elevation of phospho-eIF2α, ATF4, and CHOP in hypertension, leading to reduced cardiac damage and improved vascular function in hypertension." (PMID 26729106, 2015).
Hypertension (continued). "The species of dominant phyla and genera of ATF4 participation in the development of hypertension induced by high salt in mice did not change, but the relative abundance of dominant phyla and genera changed." (PMID 33282868, 2020). "On the basis of previous studies, we hypothesize that ATF4 regulates the balance of gut microbiota and mediates VK2 expression, which leads to endothelial dysfunction, thus participating in the development of hypertension." (PMID 33282868, 2020).
Stroke (10 papers, 2017 to 2024). Sudden impairment of blood flow to a part of the brain due to occlusion or rupture of an artery to the brain. "ATF4, implicated in ferroptotic neuronal death during stroke, demonstrated a similar induction of ferroptosis in GBM cells." (PMID 38291540, 2024). "In addition to the role of MAMs-related ISR, ATF4 also plays the protective role in stroke-associated neuroinflammation." (PMID 38321473, 2024). "In the event of a stroke, miR-383-3p-enriched exosomes from M1 microglia promoted the necroptosis of neurons via negatively regulating the expression of activating transcription factor 4 (ATF4)." (PMID 36552117, 2022). "In the nervous system, ATF4 is a key redox-regulated, pro-death transcriptional activator that propagates death responses to oxidative stress in stroke." (PMID 34163322, 2021). "We found that in the BCAO model of stroke, there was a clear increase in eIF2α, and ATF4 expression, indicating that the PERK pathway is activated in BCAO models." (PMID 31907023, 2020). "Notably, another study showed that global Atf4 knockout mice had smaller infarcts and better neurologic outcomes after stroke." (PMID 38543139, 2024). "The detrimental role of PERK activation in stroke outcomes is often implicated by pharmacologic studies in which protective effects are associated with reduced levels of PERK branch components such as p-eIF2α, ATF4, and CHOP." (PMID 38543139, 2024). "ATF4 has been shown to act as a pro-death transcriptional regulator in the nervous system that propagates death responses to oxidative stress in vitro and to stroke in vivo." (PMID 33418948, 2021). "The mRNA levels of Atf4 were slightly increased in wildtype and Grina−/− mice 6 h after stroke." (PMID 31683519, 2019). "Key proteins involved in mitochondrial stress, such as ATF5, ATF4, HSF1, FGF21, and GDF15, hold promise as potential targets for modulating neuroinflammation during stroke." (PMID 38321473, 2024). "We found that there was a marked increase in ATF4 expression, indicating that the PERK pathway is activated in the hypoxia/reoxygenation model of stroke." (PMID 37509524, 2023).
cardiomyopathy (9 papers, 2019 to 2026). A disease of the heart muscle or myocardium proper. "A recent study also highlighted ATF4’s protective role in preventing ferroptosis in cardiomyopathy caused by a Cox10 deficiency." (PMID 40227255, 2025). "Recently, growing evidence has further underscored the dual roles of ATF4 as the guardian or executioner in cardiovascular disorders, such as coronary heart disease, cardiomyopathy, arrhythmia, valvular heart disease, heart failure and cardiovascular aging." (PMID 41561820, 2026). "In cardiomyocytes, it may be transcriptionally induced by ATF4, overall driving progressive cardiac fibrosis in diseases such as arrhythmogenic and diabetic cardiomyopathies." (PMID 40301189, 2025). "Genes associated with ER stress (e.g., ATF4, NUPR1, DDIT3, TRIB3, CHAC1, SESN2, HERPUD1) were upregulated and genes related to cardiomyopathy and sarcomeric structure (e.g., MYH7, SYNPO2L, LDB3, ACTN2, MYLK3) were downregulated by afatinib, sorafenib, or high-dose ponatinib." (PMID 37069550, 2023). "Thus, understanding the regulatory mechanism of ATF4/CHOP pathway is important to develop the therapeutic strategy against cardiomyopathy." (PMID 31787756, 2019). "The rapidly progressing cardiomyopathy and heart failure observed in PRMT1 cKO within 8-weeks after birth likely is due to its role in the control of critical regulators for cardiac function such as CaMKII and ATF4 that are directly contributing to ER stress and heart failure." (PMID 31787756, 2019).